IFI27 (interferon alpha inducible protein 27)
Diseases named in the same sentence as IFI27 in open-access papers (continued):
Sharing a sentence is not in itself a finding about the gene and the disease.
gastric cancer (11 papers, 2014 to 2024). A primary or metastatic malignant neoplasm involving the stomach. "BRG1-associated expression of 9–27 and IFI-27 is involved in cisplatin resistance in gastric cancer cells." (PMID 38877473, 2024). "The splicing event of the gastric cancer drug resistance-related gene IFI27 significantly increased the selection proportion of the 3′end exon in the nintedanib treatment group." (PMID 39726754, 2024). "TRAIL-induced apoptosis in animal and cellular models of HCC and gastric cancer can be induced when IFI27 is downregulated." (PMID 35109839, 2022). "As the relationship between gastric cancer and IFI27 and other ISGs is still unclear, further studies are required." (PMID 35267998, 2022). "In animal and cell models, the down-regulation of IFI27 can promote apoptosis induced by TNF-related apoptosis-inducing ligand in hepatocellular carcinoma and gastric cancer, suggesting that IFI27 may be a key protein for tumor development." (PMID 34592906, 2021). "For example, downregulation of IFI27 can promote TRAIL-induced apoptosis in animal and cellular models of hepatocellular carcinoma and gastric cancer, suggesting that IFI27 may be a key protein for tumor development." (PMID 29580248, 2018). "In this study, a series of functional experiments have confirmed the regulation of ADAMTS16/NF-κB/IFI27 signaling axis in the development of gastric cancer, suggesting that ADAMTS16 can be regarded as a potential target for the treatment of gastric cancer." (PMID 36232317, 2022). "For instance, high expression of IFI27 can promote tumor cell proliferation, invasion, and reduced apoptosis in HCC, gastric cancer, and oral squamous cell carcinoma." (PMID 33824473, 2021).
hepatocellular carcinoma (11 papers, 2014 to 2025). A malignant tumor that arises from hepatocytes. "Therefore, it will be of interest to explore the potential involvement of IFI27 in the progression of HBV-associated chronic hepatitis, cirrhosis, and hepatocellular carcinoma in future studies." (PMID 41081508, 2025). "We showed that IFI27 is highly expressed in human hepatoma cell lines by the induction of IFN-α." (PMID 33868214, 2021). "In order to clarify the antiviral mechanism of cytokines, 36 ISGs along with IFI27, which are highly induced in liver cells, were tested for their ability to inhibit HBV replication when overexpressed in human hepatoma cells." (PMID 33868214, 2021). "We first demonstrated the high inducibility of IFI27 in human hepatocyte cells, including both hepatoma cell lines and PHHs, upon IFNα treatment, as well as the nonapoptotic antiviral activity of IFI27." (PMID 41081508, 2025). "ACSL4, GNMT, IFI27, and miR122 are known or expected to play a key role in the clinical courses of HCV-mediated liver diseases by regulating HCV replication and thereby hepatocellular carcinoma." (PMID 30138348, 2018).
pancreatic cancer (9 papers, 2006 to 2025). "A comprehensive bioinformatic analysis of the mRNA expression of IFI27 in PDAC revealed that the gene-encoding Interferon Alpha-Inducible IFI27 was significantly upregulated in pancreatic cancer tissues compared to normal tissues." (PMID 39457004, 2024). "Literature indicates that functional annotations of IFI27 in pancreatic cancer reveal its close association with cellular immunity and metabolism, particularly glycolysis, and increased IFI27 expression is associated with reduced CD8+ T cells and increased M2-type macrophages." (PMID 41008826, 2025). "In summary, genes associated with past alcohol consumption have been linked to physiological processes associated with increased risk for malignant transformation, pancreatic cancer cell proliferation, survival, invasion, metastasis, and impaired cell differentiation (K19, IFI27, S100P, CXCR4)." (PMID 17181856, 2006). "IFI27 (Interferon Alpha Inducible Protein 27) has been proposed as a potential prognostic biomarker in pancreatic cancer, where its overexpression correlates with increased cell proliferation, metastasis, and malignant progression." (PMID 41008826, 2025). "IFI27 has been previously identified as a prognostic marker for pancreatic cancer, and involved in pancreatic cancer migration and invasion." (PMID 36010660, 2022). "In summary, our single-cell RNA sequencing and bioinformatics analysis identified several highly variable genes including IFI27, KRT18, KRT19, MMP1, MMP3, and NEFL, whose expression is associated with a shorter overall survival of pancreatic cancer patients." (PMID 36010660, 2022). "The results from TCGA database inferred that IFI27 expression is high in pancreatic cancer compared with that in normal tissues." (PMID 33824473, 2021). "Our results revealed that upregulation of IFI27 in PAAD can promote the progression of pancreatic cancer." (PMID 34592906, 2021). "A mouse orthotopic cancer model was utilized to demonstrate that IFI27, glycolysis and M2 macrophages were significantly up-regulated in pancreatic cancer." (PMID 34592906, 2021). "Accordingly, in our report, the clinical correlation analysis showed that the expression of IFI27 in pancreatic cancer with low malignancy was significantly lower than that of high malignant pancreatic cancer." (PMID 34592906, 2021). "Through our comprehensive analysis, we found that IFI27 is significantly increased in pancreatic cancer tissues, and pathway enrichment found that IFI27 is mainly related to cellular immunity and metabolism." (PMID 34592906, 2021). "Overall, in this study we found a new biomarker, IFI27, to assist the early diagnosis and prognosis of pancreatic cancer." (PMID 34592906, 2021). "The results obviously suggest that IFI27 mRNA is expressed at a higher level in pancreatic tumor tissues." (PMID 34592906, 2021). "The overexpression of the IFIT3 and IFI27 genes has been reported to induced tumour proliferation, angiogenesis and chemoresistance in pancreatic carcinoma cells." (PMID 24270600, 2014). "Additionally, higher mRNA expression of IFI27 was found to be negatively correlated with the overall survival rate of pancreatic cancer patients." (PMID 39457004, 2024). "Moreover, we also found that the expression of IFI27 has a significant impact on the tumor immune microenvironment of pancreatic cancer." (PMID 34592906, 2021). "Therefore, TIMER was utilized to explore the potential relationship between IFI27 expression and the abundance of infiltrated immune cells in pancreatic cancer." (PMID 34592906, 2021). "In addition, we wished to gain a measure of how different the TIME of patients with high IFI27 expression in pancreatic cancer is entirely different from that of patients with low expression of IFI27." (PMID 34592906, 2021). "Gene Set Enrichment Analysis (GSEA) showed that IFI27 may be involved in glycolysis, myc targets v2 and mTORC1 signaling, thereby promoting progression of pancreatic cancer." (PMID 34592906, 2021).
pancreatic cancer (continued). "However, the impact of IFI27 in the progression of pancreatic cancer remains to be elucidated." (PMID 34592906, 2021). "A total of 26 genes were found to be significantly associated with poor prognosis, while five of them, including SYT12, GJB5, RHOJ, GJB3 and IFI27, were of particular interest as they have not been previously associated with poor outcomes in pancreatic cancer cases." (PMID 32724299, 2020). "Previous studies have indicated that in esophageal squamous cell carcinoma, PABPC1 fosters both angiogenesis and malignant progression by inducing IFI27 mRNA stability, and PABPC1 de‐ubiquitinated by USP10 promotes the stability of CLK2 mRNA to facilitate the development of pancreatic cancer." (PMID 40013670, 2025). "We speculate that IFI27 may affect the tumor microenvironment (TME) of PAAD by regulating cellular immunity and metabolism, thereby promoting the progression of pancreatic carcinoma and worsening the prognosis." (PMID 34592906, 2021). "While IFI27 has been shown to be a key gene in several types of cancer, studies have not yet identified relationships between IFI27 expression and the progression of pancreatic carcinoma." (PMID 34592906, 2021).
respiratory infections (8 papers, 2020 to 2024). "IFI27 has been described in a separate study as a novel single-gene biomarker in patient blood that was able to discriminate, with 88% diagnostic accuracy and 90% specificity, between influenza virus- and bacterium-associated respiratory infections." (PMID 32184234, 2020). "In respiratory infections, IFI27 expression has been shown to discriminate bacterial from viral illness." (PMID 34442377, 2021).
cholangiocarcinoma (7 papers, 2020 to 2024). A carcinoma that arises from the intrahepatic biliary tree (intrahepatic cholangiocarcinoma) or from the junction, or adjacent to the junction, of the right and left hepatic ducts (hilar cholangiocarcinoma). "Clinically, higher expression of IFI27 was associated with worse overall survival in patients with Cholangiocarcinoma." (PMID 39457004, 2024). "Deregulation of IFI27 expression has been reported in cholangiocarcinoma patients that are associated with poor survival." (PMID 32592372, 2020). "Another study showed that overexpression of IFI27 increased the proliferation, migration, and invasion of Cholangiocarcinoma cells." (PMID 39457004, 2024). "Mechanically, IFI27 induces epithelial–mesenchymal transition (EMT) to promote cholangiocarcinoma metastasis." (PMID 35346324, 2022). "It has been reported that the key gene that we uncovered, IFI27, is an oncogene that correlates with poor survival in cholangiocarcinoma." (PMID 34592906, 2021). "Moreover, IFI27 mediated epithelial–mesenchymal transition (EMT) to promote cholangiocarcinoma metastasis." (PMID 35346324, 2022). "Interferon α-inducible protein 27 (IFI27) is involved in innate immunity and the elevated expression of IFI27 could enhance the proliferation, migration, and invasion of cells in cholangiocarcinoma." (PMID 34393665, 2021).
melanoma (7 papers, 2016 to 2023). A malignant, usually aggressive tumor composed of atypical, neoplastic melanocytes. "In melanoma patients treated with anti-PD1 and cetirizine combination therapy, upregulations of IFI27, IFIT1, and IFIT3 are associated with M1 polarization of macrophages and improved patient outcome." (PMID 37174688, 2023). "Using cetirizine in advanced immunotherapy for melanoma patients induces M1 macrophage polarization through the IFI27-related INF-γ pathway." (PMID 37762054, 2023). "However, we also identified three interferon-stimulated genes (ISGs)—IFI6, IFI27, and MX1—that have not been previously implicated in oncogenic NRAS-induced transformation and melanoma tumor growth." (PMID 27608486, 2016). "We detected ISG.RS mRNA level in negative control or SOX2 KD melanoma cell lines and observed that SOX2 KD decreased the ISG.RS expression (IDO1, PDL1, IFI27, and USP16)." (PMID 33158915, 2020).
Sjögren’s syndrome (7 papers, 2014 to 2024). "Several studies have reported that IFI27 is an immune biomarker for many autoimmune diseases, such as dermatomyositis, Sjögren’s syndrome, ANCA-associated vasculitis, SLE, the expression of which is increased significantly, and is likely involved in the immunoregulation of these diseases." (PMID 39080788, 2024). "The interferon (IFN)-response gene IFI27 exhibits significantly increased expression in patients a chronic autoimmune disease, Sjögren’s syndrome, compared with control individuals." (PMID 26359667, 2015). "Patient TN2 was undergoing treatment with soluble tumor necrosis factor-alpha (TNF-α)/lymphotoxin-alpha (LT-α) receptor for therapy of rheumatoid arthritis with Sjögren syndrome at the time of collection; IFI27 expression could be indirectly induced by this treatment." (PMID 27100186, 2016). "Finally, we examined this IRG signature (ISG15, SIGLEC1, STAT1 RSAD2, IFI27 and IFI44L) in peripheral blood mononuclear cells (PBMCs) collected from a smaller cohort of healthy controls, disease controls, AAV and primary Sjogren’s syndrome (pSS) patients." (PMID 33859290, 2021).
psoriasis (6 papers, 2018 to 2023). An autoimmune condition characterized by red, well-delineated plaques with silvery scales that are usually on the extensor surfaces and scalp. "Interferon alpha-inducible protein 27 (IFI27) maps chromosome 14q32, which is located at a psoriasis susceptibility locus." (PMID 35075118, 2022). "IFI27 (interferon α–inducible protein 27) is involved in the proliferation of skin keratinocytes, both in imiquimod-induced psoriasis-like skin and in HaCaT cells." (PMID 36172384, 2022). "ISG15, MX1, IFI44L, and IFI27 were the characteristic psoriasis genes found in suprabasal keratinocytes." (PMID 36172384, 2022). "ISG15, MX1, IFI44L, and IFI27 were the characteristic genes of psoriasis in suprabasal keratinocytes." (PMID 36172384, 2022). "Up-regulation of the IFI27 gene was previously reported in psoriasis, diffuse large B-cell lymphoma and fatigued patients after radiation therapy." (PMID 33228694, 2020). "Increased transcripts of IFI27 within VA and slightly less in noVA tissues, also reported in rheumatoid arthritis (RA), psoriasis, and UC, were especially observed in NV+ tissue samples and probably reflect a mixed response of IFN type I/III in an IFN-γ/TNF-α-enriched environment." (PMID 36282455, 2023).
dengue (5 papers, 2020 to 2023). "Nuclear Enriched Abundant Transcript 1 (NEAT1), which is a non-coding RNA, and the coding gene Interferon alpha-inducible protein 27 (IFI27) were highly co-expressed and negatively associated with the degree of dengue severity." (PMID 33330133, 2020). "The GO analysis revealed that the genes BUB1, RRM2, IFI27, DLGAP5, and CEP55 exhibit 4-fold up-regulation in dengue and SD patients however, they exhibit downregulation in CP." (PMID 38076406, 2023). "IFI27 and TPX2 have also been highlighted in the context of dengue virus infection by other studies." (PMID 35220956, 2022). "In addition, IFI27 was predominantly upregulated across disease phases in DHF and DSS, being a putative late-stage biological indicator for severe dengue." (PMID 37638052, 2023). "IFI27, TPX2, CDT1 and CDCA3 are particularly known for their role in cancer, and TPX2 also for its role in the context of infectious diseases, in particular dengue fever." (PMID 35220956, 2022).
HIV-1 infection (5 papers, 2013 to 2024). The type species of lentivirus and the etiologic agent of acquired immunodeficiency syndrome (AIDS). "We found that HIV-1 infection induced the expression of a set of ISGs (RSAD2, ISG15, IFI44L, and IFI27) that remained upregulated during the chronic phase of HIV-1 infection." (PMID 39104769, 2024). "Intriguingly, among the ISGs found to be more robustly induced by HIV-1 infection than SIVmac239 infection in NPMs was interferon alpha inducible protein 27 (IFI27), which was shown to more potently inhibit HIV-1 infection than human IFI27." (PMID 39459950, 2024). "In addition, an interferon-stimulated gene, interferon alpha inducible protein 27, was upregulated in acute HIV-1 infection and acquired an enhanced ability to inhibit HIV-1 replication compared with its human ortholog." (PMID 37134013, 2023). "After HIV-1 infection, upregulation of a cluster of ISGs (RSAD2, ISG15, IFI44L, and IFI27), as compared to pre-SC, emerged and the expression of these ISGs remained high during the untreated course of infection." (PMID 39104769, 2024).
asthma (4 papers, 2022 to 2023). "Additionally, the genes involved in proinflammatory function (ITGB2 and FABP4) and apoptosis process (IFI27) were elevated in asthma." (PMID 36439114, 2022).
autoimmune disease (4 papers, 2014 to 2024). A disorder resulting from loss of function or tissue destruction of an organ or multiple organs, arising from humoral or cellular immune responses of the individual to their own tissue constituents. "The aberrant expression of IFI27 is also involved in the development of several autoimmune diseases." (PMID 37638007, 2023).
Immunodeficiency (4 papers, 2014 to 2023). Failure of the immune system to protect the body adequately from infection, due to the absence or insufficiency of some component process or substance. "Suggested that IFI27 may contribute to the mechanism of immunodeficiency, HIV replication, in HIV-1 disease." (PMID 35068272, 2022). "We concluded that IFI27 may be a biomarker for various immune diseases." (PMID 37383223, 2023).
pancreatic adenocarcinoma (4 papers, 2021 to 2025). "Furthermore, IFI27 was found to be closely associated with the clinical progression of pancreatic adenocarcinoma (PAAD), tumor glycolysis, and M2 macrophage infiltration." (PMID 35267998, 2022). "Compared with normal pancreas tissue samples, significantly upper level of IFI27 mRNA was observed in the cohort of pancreatic adenocarcinoma from Oncomine (right)." (PMID 34592906, 2021). "Pancreatic adenocarcinoma tumors exhibit increased levels of mRNA expression for components of the Transforming growth factor-β pathway (TGFB1/2/3, TGFBR1/2/3) and Interferon Type I pathways (IFNAR1, STAT1, IRF9 and IFI27)." (PMID 39457004, 2024).
bronchiolitis (3 papers, 2006 to 2026). Inflammation of the bronchioles characterized by swelling of the bronchioles and mucus accumulation. "The present study identified the genes IFI27 and CLC to be highly differentially expressed in whole blood of infants hospitalised with RSV, subtype B, bronchiolitis of moderate severity." (PMID 17166282, 2006). "IFI27, together with other genes that were differentially expressed, such as IFI44, OAS3, EPSTII, and IFI44L, are generally significantly up-regulated in whole blood from infants admitted to hospital with severe RSV-bronchiolitis." (PMID 36622786, 2023). "The gene IFI27 is upregulated and the gene CLC is downregulated in whole blood of infants hospitalised with RSV, subtype B, bronchiolitis and is not reported before." (PMID 17166282, 2006). "We found the interferon, alpha-inducible protein 27 (IFI27) and Charcot-Leyden crystal protein (CLC) to be the most differentially expressed genes in this study and not to be reported before in conjunction with acute viral bronchiolitis." (PMID 17166282, 2006).
colorectal cancer (3 papers, 2022 to 2025). A primary or metastatic malignant neoplasm that affects the colon or rectum. "(D) Colorectal cancer (CRC) tissue mRNA levels of IFI27 and OAS1 were determined by qRT-PCR, and (E) their relationships with VPS9D1-AS1 were calculated with Pearson correlation analysis." (PMID 36458816, 2022). "To create an endogenous type I IFN reporter, we chose the colorectal cancer cell line HCT116, which is highly efficient for CRISPR-based gene editing, and surveyed IFNα induction of canonical type I IFN target genes (IFIT1, IFIT2, IFIT3, IFI27, IRF7, OASL, RSAD2)." (PMID 38358346, 2024). "Notably, IFI27 was linked to the symptomatic non-disease control group, DEFA4 to the non-advanced adenoma group, MPO to the advanced adenoma group, and CD177 to the colorectal cancer group." (PMID 40003985, 2025).
lymphoma (3 papers, 2014 to 2024). A malignant (clonal) proliferation of B- lymphocytes or T- lymphocytes which involves the lymph nodes, bone marrow and/or extranodal sites. "For example, IFI27 involves in the IRF4 regulatory network, which is implicated in MDS, leukemia, myeloma and lymphoma." (PMID 36713414, 2022). "The epidemiological findings that pyothorax-associated lymphoma, which is strongly associated with EBV, expresses IFI27 mRNA supports our findings, although the expression of BNRF1 in that lymphoma has not been assessed." (PMID 38300891, 2024). "In addition, we have identified a panel of novel transcriptional targets including IFI27, IFI44, GBP1, CFLAR and ARHGAP18 for IRF4 in lymphomas." (PMID 25207815, 2014).